SNORD115-16 (small nucleolar RNA, C/D box 115-16)
Synonyms: HBII-52-16
Gene: Small nucleolar RNA gene on chromosome 15 (25,199,448 to 25,199,529, forward strand). Ensembl gene ENSG00000200757.
Gene Ontology:
Biological process: RNA processing
Cellular component: nucleolus
Homologues: Paralogues in human: SNORD115-11 (99% identical), SNORD115-13 (99% identical), SNORD115-29 (99% identical), SNORD115-36 (99% identical), SNORD115-43 (99% identical), SNORD115-12 (98% identical), SNORD115-22 (98% identical), SNORD115-26 (98% identical), SNORD115-39 (98% identical), SNORD115-40 (98% identical), SNORD115-44 (98% identical), SNORD115-6 (98% identical), and 37 more.